CTNNA2 (catenin alpha 2)
Diseases named in the same sentence as CTNNA2 in open-access papers (continued):
Sharing a sentence is not in itself a finding about the gene and the disease.
osteoporosis (1 paper, 2020). A condition of reduced bone mass, with decreased cortical thickness and a decrease in the number and size of the trabeculae of cancellous bone (but normal chemical composition), resulting in increased fracture incidence. "MTAG analysis identified several novel candidate genes, such as CTNNA2 (MTAG P value = 2.24 × 10−6) for SCZ and FADS2 (MTAG P value = 2.66 × 10−7) for osteoporosis." (PMID 32107650, 2020).
Pachygyria (1 paper, 2021). Pachygyria is a malformation of cortical development with abnormally wide gyri with sulci 1,5-3 cm apart and abnormally thick cortex measuring more than 5 mm (radiological definition). "Loss of function mutations within CTNNA2 are thought to be one of the factors underlying pachygyria, characterized by loss of neurite stability and migration." (PMID 34035472, 2021).
tumor (23 papers, 2016 to 2024). "Analysis of the cohort from the Cancer Genome Atlas showed that patients with CTNNA2 mutation had more tumor neoantigens and a greater tumor mutation burden (TMB)." (PMID 34163353, 2021). "Mutation of CTNNA2 is associated with tumor invasiveness and thus inhibition of transcription of the gene is desirable." (PMID 30915033, 2019). "Notably, the results showed that GBAs already have some tumour‐related gene mutations, such as CTNNA2, CTNNB1, and KChIP3, which regulate the cell cycle and apoptosis." (PMID 35075805, 2022). "In addition, mutation of one of the catenin genes, CTNNA1, which functions as a tumor suppressor in normal conditions, leads to susceptibility to gastrointestinal tract cancers, and mutation of the other catenin gene, CTNNA2, is associated with tumor invasiveness." (PMID 31600974, 2019). "Interestingly, in ML10 CDH1WT where the DCIS was profiled, promoter methylation of WNT pathway genes were detected in the Abr component, including APC and CTNNA2 and may reflect the earlier divergence and underlying drivers of abrogated cell–cell adhesion in this tumour." (PMID 35053458, 2022). "CTNNA2 was expressed in these invasive regions, though was also expressed at high levels in other regions of the tumor." (PMID 34849760, 2022). "Catenin Alpha (CTNNA1 and CTNNA2) expression was also down-regulated in cancerous tissues, which was consistent to well-reported tumor-suppressor functions of CTNNA1 and CTNNA2 in various cancers." (PMID 33335165, 2020). "To explore the function of α-N-catenin in vivo, we subcutaneously injected cells with CTNNA2 overexpression and their controls into athymic nude mice for tumor growth analysis." (PMID 31489113, 2019). "However, the number of mitosis cell in CTNNA2 tumor tissue was decreased significantly, approximately 73% of control tumors." (PMID 31489113, 2019). "Our results not only confirm the role of CTNNA2 mutation in LUAD but also suggest that the effect of CTNNA2 may occur via changes to the immune microenvironment, providing strong evidence for CTNNA2 as a new tumor microenvironment therapeutic target." (PMID 34163353, 2021). "We next sought to confirm whether CTNNA2 acts as a tumor suppressor in in vivo." (PMID 31489113, 2019). "Aside from CTNNA1, CTNNA2, and CTNNB1, there was low expression of most catenins in the tumor samples (P < 0.001) compared with the controls." (PMID 37924160, 2023). "We found that compared with CTNNA2-WT patients, CTNNA2-MT patients had a significantly higher TMB and more tumor neoantigens (Mann-Whitney U test, p < 0.05)." (PMID 34163353, 2021). "The expressions of CTNNA2 and NSE, a neuronal marker, in tumor tissues were confirmed in dissected tissues using immunohistochemical staining." (PMID 31489113, 2019). "To confirm CTNNA2 mediated angiogenesis inhibition in vivo, we performed CD31/PECAM-1 (Platelet Endothelial Cell Adhesion Molecule-1) immunohistochemical staining on tumor sections from mice and counted the blood vessels." (PMID 31489113, 2019). "In total, recurrent (>3) MEI were observed in 329 protein-coding genes of which 28 genes are annotated in the Cancer Gene Consensus with either oncogenic (ALK1, ERBB4, TSHR, PREX2, CTNNA2, CTNND2) or tumour suppression roles (EBF1, LRP1B, PTPRD, GPC5, ROBO2, PTPRT)." (PMID 35301290, 2022). "Notably, three members from the catenin super family, CTNNA1, CTNNA2, CTNNA3, were found to be dysregulated in tumor tissues." (PMID 36361574, 2022). "In further support of the influence of the tumor microenvironment on miRNA expression changes in OS, miRNA–gene interaction analysis identified potential interactions between miR-223 and adhesion proteins DST and CTNNA2." (PMID 33937369, 2021). "In terms of the genes that are exclusively affected by tumor-specific somatic TE insertions, we also observed the enrichment of affected genes in the cancer pathway (due to tumor-specific TE insertions in genes such as COL4A6, PLCB4, ARNT2, LRP5, NCOA3, and CTNNA2)." (PMID 35013466, 2022).
cancer (12 papers, 2011 to 2025). A tumor composed of atypical neoplastic, often pleomorphic cells that invade other tissues. "It is of interest to note that GBA organoids already have mutations in some cancer‐related genes (e.g., CTNNA2 and CTNNB1), suggesting the malignancy potential of some GBA cells." (PMID 35075805, 2022). "Nonsynonymous mutations in four cancer-associated genes, CTNNA2 (11.1% vs. 5.8%; log10 p-value = −0.6), FLG (8.9% vs. 4.3%; log10 p-value = −0.6), GNAS (4.4% vs. 1.4%; log10 p-value = −0.5), and BCORL1 (17.0% vs. 11.6%; log10 p-value = −0.5), were more abundant in the case group." (PMID 32566745, 2020). "The main pathways of methylome biomarkers were associated with calcium signalling (CACNA1E, RYR2, RYR3), cancer pathways (DCC, RASSF1, WNT1, CTNNA2), multiple neurodegenerative diseases (WNT1, DNAI1, RYR2, RYR3), immune system disorders and cell adhesion (HLA-DRA, HLA-DRB1, HLA-DRB5)." (PMID 40524349, 2025). "VLCKD-induced nutritional ketosis promoted changes in the methylation of 18 genes (20 CpGs; 17 hypomethylated, 3 hypermethylated) belonged to cancer-related pathways with MAPK10, CCN1, CTNNA2, LAMC3 and GLI2 being the most representative genes." (PMID 40140215, 2025). "Genome-wide methylation-associated biomarkers were involved in the pathways of neurodegeneration-multiple diseases (13%), cancer-related pathways (DCC, RASSF1, WNT1, CTNNA2; 13%), and Hippo, calcium signalling, cell adhesion and immune system-related pathways (all 10%)." (PMID 40524349, 2025).
psychiatric disorder (2 papers, 2021 to 2023). A disorder characterized by behavioral and/or psychological abnormalities, often accompanied by physical symptoms. "Our study suggests that the identified SNP of the CTNNA2 gene is associated with rumination, and this type of perseverative negative thinking mediates a wide variety of psychopathologies and psychiatric disorders." (PMID 34577549, 2021). "AlphaN-catenin gene CTNNA2 has been implicated in intrauterine brain development, as well as in several psychiatric disorders and cardiovascular diseases." (PMID 34577549, 2021). "Although having a prominent role in intrauterine stages, CTNNA2 is also expressed in the adult brain, showing different levels in patient groups versus controls, underpinning its potential as a drug target for psychiatric disorders." (PMID 34577549, 2021).
CTNNA2 also shares sentences with these, for which no sentence is quoted: neurodevelopmental disorder (4 papers); autism (2); bipolar disorder (2); Anorexia (1); attention deficit-hyperactivity disorder (1); cardiovascular diseases (1); cyst (1); dental caries (1); endometrial cancer (1); glioma (1); heart diseases (1); HIV-1 infection (1); Huntington disease (1); Hypertension (1); immune system disorder (1); infection (1); lung adenocarcinoma (1); metabolic disease (1); musculoskeletal diseases (1); neurodegenerative disease (1); oropharyngeal squamous cell carcinomas (1); pancreatic cancer (1); pancreatic ductal adenocarcinoma (1); pharyngeal cancer (1); Stroke (1); urinary system diseases (1).